RNU6-653P (RNA, U6 small nuclear 653, pseudogene)
Gene: Small nuclear RNA gene on chromosome 6 (109,059,509 to 109,059,614, reverse strand). Ensembl gene ENSG00000199944.
Homologues: Orthologues: macaque U6 (94% identical), dog U6 (89% identical), mouse Gm23461 (87% identical), guinea pig U6 (75% identical). Paralogues in human: RNU6-698P (90% identical), RNU6-1251P (89% identical), RNU6-140P (89% identical), RNU6-16P (89% identical), RNU6-25P (89% identical), RNU6-29P (89% identical), RNU6-33P (89% identical), RNU6-38P (89% identical), RNU6-46P (89% identical), RNU6-480P (89% identical), RNU6-891P (89% identical), RNU6-959P (89% identical), and 1285 more.